LUZP2 (leucine zipper protein 2)
Synonyms: KFSP2566; PRO6246
Tractability: Antibody: UniProt places it where antibodies can reach, with high confidence; UniProt predicts a signal peptide or a membrane-spanning region; its Gene Ontology location is reachable by antibodies, with medium confidence; the Human Protein Atlas places it where antibodies can reach. PROTAC: ubiquitination databases record sites on it; its protein half-life has been measured.
Gene: Protein-coding gene on chromosome 11 (24,496,970 to 25,082,638, forward strand). Ensembl gene ENSG00000187398.
Subcellular location: Secreted
Subcellular location (Human Protein Atlas): Cytosol; Nucleoplasm; Plasma membrane; Predicted to be secreted
Gene Ontology:
Cellular component: extracellular region
Genetic constraint (gnomAD): Loss-of-function variants: 9 observed, 12.79 expected, observed/expected ratio (o/e) 0.7, 90% interval 0.42 to 1.23. The upper end of that interval is the gene's LOEUF score, 1.23, which puts it in group 5 of 6, group 1 being the genes least tolerant of losing a copy. Missense variants: 159 observed, 148.38 expected, observed/expected ratio (o/e) 1.07, 90% interval 0.94 to 1.22. Synonymous variants: 52 observed, 50.13 expected, observed/expected ratio (o/e) 1.04, 90% interval 0.83 to 1.31.
Homologues: Orthologues: chimpanzee LUZP2 (99% identical), macaque LUZP2 (97% identical), rabbit LUZP2 (85% identical), rat Luzp2 (84% identical), mouse Luzp2 (83% identical), pig LUZP2 (73% identical), dog LUZP2 (73% identical), tropical clawed frog luzp2 (58% identical), zebrafish luzp2 (50% identical).
Diseases named in the same sentence as LUZP2 in open-access papers:
LUZP2 is named in the same sentence as 29 diseases in open-access papers, as found by Europe PMC text mining. Sharing a sentence is not in itself a finding about the gene and the disease. The quoted sentences say what the papers report.
Wilms tumor (4 papers, 2016 to 2022). An embryonal neoplasm characterized by the presence of epithelial, mesenchymal, and blastema components. "LUZP2(leucine zipper protein 2 gene), located on Chr 11p13–11p14 and encoding a leucine zipper protein, has been shown to be deleted in Wilms' tumor patients." (PMID 36056349, 2022). "LUZP2 is a leucine zipper protein coding gene that has been reported to be deleted in some patients with Wilms tumor-Aniridia-Genitourinary anomalies-mental Retardation (WAGR) syndrome." (PMID 29747637, 2018). "LUZP2 has been reported to be deleted in patients with Wilms' tumor-Aniridia-Genitourinary anomalies-mental Retardation (WAGR) syndrome, which is a scarce congenital anomaly syndrome consisting of Wilms' tumor, genital anomalies, aniridia, and mental retardation." (PMID 32695826, 2020).
glioma (3 papers, 2020 to 2022). A benign or malignant brain and spinal cord tumor that arises from glial cells (astrocytes, oligodendrocytes, ependymal cells). "In terms of overall survival, low-expression of LUZP2 was significantly associated with poor prognosis in lower grade glioma (LGG), lung squamous cell carcinoma (LUSC), kidney renal clear cell carcinoma (KIRC) and prostate adenocarcinoma (PRAD)." (PMID 36109820, 2022). "In the process of glioma production and increased malignancy, the acquisition, loss, and reacquisition of LUZP2 are interesting." (PMID 32695826, 2020). "In this study, we search the expression profile and clinical significance of LUZP2 to investigate the potential mechanisms of its regulation and underlying biological function in low-grade glioma by data mining in The Cancer Genome Atlas (TCGA) and Chinese Glioma Genome Atlas (CGGA)." (PMID 32695826, 2020). "The TF regulatory network will lay the foundation for future research on the mechanism of action of LUZP2 in gliomas." (PMID 32695826, 2020). "In view of the significant decrease of LUZP2 with the increase of glioma grade, we further study the relationship between LUZP2 and tumor subtypes." (PMID 32695826, 2020). "Through this study, it is possible that MXI1 can also suppress the glioma through LUZP2 which is still to be explored." (PMID 32695826, 2020). "Combined with the role of LUZP2 coexpression genes in GO analysis, we make a bold speculation that LUZP2 in glioma can be an important regulator involved in the regulation of neuroendocrine function and development of extracellular matrix." (PMID 32695826, 2020). "Through GEPIA and the expression profile of LUZP2 in TCGA, CGGA, and GSE16011, we found that, as in prostate cancer, the expression of LUZP2 mRNA in gliomas was upregulated compared with normal brain tissue but downregulated during the development from low to high grade." (PMID 32695826, 2020). "Through TCGA and CGGA part B and part C dataset, we explored the relationship between LUZP2 and glioma grade, histology classification, IDH mutant status, 1p19q codeletion status, and whether the tumor is a recurrent sample." (PMID 32695826, 2020). "It has been reported that LUZP2 is a positive modulator of neuroendocrine differentiation, and the possible role of the LUZP2 in glioma may be related to it." (PMID 32695826, 2020). "More datasets are needed to verify the exact role of LUZP2 in glioma." (PMID 32695826, 2020). "The present study further explored the predictive ability of LUZP2 on the prognosis of glioma." (PMID 32695826, 2020). "Although the interaction between miR-142-5p and LUZP2 has been found in the miRTarBase dataset, it is still unclear whether they have any interaction in gliomas." (PMID 32695826, 2020). "This indicates that the decrease of LUZP2 may be an important sign of gliomas transforming from low grade to high grade." (PMID 32695826, 2020). "Overall, our analysis emphasized the importance of LUZP2 in low-grade glioma and established a complete regulatory network from transcription factors to miRNA to downstream signaling pathways, which provided great convenience for the in vitro intervention experiment." (PMID 32695826, 2020). "The role of HEY1 in gliomas may be very closely related to its effect on LUZP2." (PMID 32695826, 2020). "However, the relationship between LUZP2 and glioma histology is still uncertain." (PMID 32695826, 2020). "By data mining in The Cancer Genome Atlas (TCGA) and Chinese Glioma Genome Atlas (CGGA), the expression, clinical characteristics, and potential regulatory mechanism of LUZP2 in LGG were assessed." (PMID 32695826, 2020). "From the analysis of the correlation between the molecular expression and the clinical subtypes, we could find that LUZP2 of IDH mutant cells decreased, which indicates that the neuroendocrine function of IDH mutant glioma cells is worse, which may be related to the role of IDH." (PMID 32695826, 2020).
glioma (continued). "The low expression of LUZP2 was closely related to grade III gliomas, IDH wild-type gliomas, 1p19q noncodeletion gliomas, and recurrent gliomas." (PMID 32695826, 2020).
prostate carcinoma (3 papers, 2018 to 2022). A carcinoma that arises from epithelial cells of the prostate gland. "It has also been reported that LUZP2 was associated with prostate cancer and hypereosinophilic syndrome." (PMID 29747637, 2018). "In LGG, adrenocortical carcinoma, and prostate cancer tissues, the expression of LUZP2 was higher than that of matched normal tissues." (PMID 32695826, 2020). "It is reported that LUZP2 mRNA expression is upregulated in hormone-naive prostate cancer (PC) compared with normal prostate tissues but downregulated during the development from hormone-naive PC to castration-resistant prostate cancer (CRPC)." (PMID 32695826, 2020). "Furthermore, Zhao et colleagues found that LUZP2 mRNA expression is elevated in hormone-naive prostate cancer (PC) relative to normal prostate tissues, but downregulated throughout the progression from hormone-naive PC to castration-resistant PC (CRPC)." (PMID 36056349, 2022).
schizophrenia (3 papers, 2005 to 2022). A major psychotic disorder characterized by abnormalities in the perception or expression of reality. "Luzp2 is found to be associated with AD, schizophrenia, intelligence and verbal memory, and the level of Lsamp is increased in both patients with depression and schizophrenia." (PMID 36142685, 2022). "In summary, in the present study we observed the association with cognitive performance estimated by MoCA for genetic variants in the LUZP2 and FBXO40 genes previously linked to the AD and schizophrenia in GWA studies." (PMID 29850221, 2018).
Atrophy (2 papers, 2018 to 2020). Any weakening or degeneration, especially through lack of use. "A genome-wide association study shows that rs7943454 in LUZP2 was associated with plasma NFL with suggestive levels and rs7943454 in LUZP2 was associated with the onset risk of AD and atrophy of the right middle temporal gyrus in the whole cohort." (PMID 32695826, 2020). "Rs7943454 in LUZP2 was associated with the onset risk of AD and atrophy of right middle temporal gyrusin the whole cohort." (PMID 29747637, 2018). "The minor allele (T) of rs7943454 within LUZP2 increased the onset risk of AD and was associated with atrophy of right middle temporal gyrus in the entire cohort of the one-year longitudinal study." (PMID 29747637, 2018). "Furthermore, the minor allele (T) of rs7943454 within LUZP2 increased the onset risk of AD (odds ratio = 1.547, confidence interval 95% = 1.018–2.351) and was associated with atrophy of right middle temporal gyrus in the whole cohort in the longitudinal study (P = 0.0234)." (PMID 29747637, 2018).
adenocarcinoma of the breast (1 paper, 2017). "CELF1 has been found involved in previous fusions with five different partners: with MTCH2 and MYOM1 in SCC and adenocarcinoma of the lung, respectively; with LUZP2 and ARFGAP2 in adenocarcinoma of the breast; and with BBOX1 in grade I-II astrocytoma of the brain." (PMID 28186972, 2017).
Alzheimer disease (1 paper, 2018). A progressive, neurodegenerative disease characterized by loss of function and death of nerve cells in several areas of the brain leading to loss of cognitive function such as memory and language. "In the present study we examined the association of two intronic variants in LUZP2 and FBXO40, previously reported genome-wide significant for the late-onset Alzheimer's disease, with the cognitive performance in a normal elderly population." (PMID 29850221, 2018).
attention deficit-hyperactivity disorder (1 paper, 2018). A disorder characterized by a marked pattern of inattention and/or hyperactivity-impulsivity that is inconsistent with developmental level and clearly interferes with functioning in at least two settings (e.g. at home and at school). "Haplotypes around intronic rs1021261 in the LUZP2 gene were genome-wide significantly associated with the intelligence in an ancestrally homogeneous family sample of individuals with at least one child affected by attention-deficit hyperactivity disorder (ADHD)." (PMID 29850221, 2018).
brain tumors (1 paper, 2020). "LUZP2 is a protein limitedly expressed in the brain and spinal cord, while there are few studies on it in brain tumors." (PMID 32695826, 2020).
Cognitive impairment (1 paper, 2022). Abnormal cognition is characterized by deficits in thinking, reasoning, or remembering. "In addition, we found some potential PD marker genes associated with AST that are linked with cognitive impairment, and the highly expressed genes (Luzp2 and Lsamp) of the activated subclusters in PD were distributed in the hippocampus in the Allen Brain Atlas." (PMID 36142685, 2022).
dementia (1 paper, 2018). Loss of intellectual abilities interfering with an individual's social and occupational functions. "No direct functional evidence of the involvement of LUZP2 or FBXO40 proteins in neurodegenerative process in AD and dementia has been found." (PMID 29850221, 2018).
mastitis (1 paper, 2021). Inflammation of breast tissue during lactation or postpartum due to an obstructed duct or infection. "Furthermore, previously known mastitis related genes such as LUZP2, AKAP8 and MEGF10 were also identified in our study as candidate genes for SCS in the RB breed." (PMID 34680890, 2021).
melanoma (1 paper, 2015). A malignant, usually aggressive tumor composed of atypical, neoplastic melanocytes. "In the context of this study aimed at characterizing the genomic landscape of melanoma, there is space to discuss somatic mutations of two new, highly significant genes, TMEM216 and LUZP2." (PMID 25600636, 2015).
Parkinson disease (1 paper, 2025). A progressive degenerative disorder of the central nervous system characterized by loss of dopamine producing neurons in the substantia nigra and the presence of Lewy bodies in the substantia nigra and locus coeruleus. "Notably, LUZP2, CLO1, and MYH6 genes were also associated with Parkinson’s disease in PheWASs." (PMID 40826483, 2025).
Tinnitus (1 paper, 2024). Tinnitus is an auditory perception that can be described as the experience of sound, in the ear or in the head, in the absence of external acoustic stimulation. "An additional locus was identified on chromosome 11 in LUZP2 with opposite effect in tinnitus and HD, predominantly seen in pillar cells with little or no expression in the cochlea otherwise." (PMID 38242899, 2024).
cancer (3 papers, 2019 to 2022). A tumor composed of atypical neoplastic, often pleomorphic cells that invade other tissues. "We detected that the LUZP2 level was negatively associated with TILs in most cancers, including LGG, LUSC, PRAD, and KIRC, while the LUZP2 methylation showed the opposite results." (PMID 36109820, 2022). "In conclusion, the results of our initial pan-cancer investigation provided a somewhat thorough understanding of the functions of LUZP2 on KIRC, LGG, PRAD, and LUSC." (PMID 36109820, 2022). "In this study, we aimed to perform a pan-cancer analysis of leucine zipper protein 2 (LUZP2)." (PMID 36109820, 2022). "Currently, little research has been done on the relationship between LUZP2 and cancers." (PMID 32695826, 2020). "Compared to normal samples, we observed that the LUZP2 mRNA expression was significantly upregulated in LGG, PRAD, LUSC and downregulated in KIRC and other eleven cancer species patients." (PMID 36109820, 2022).
tumor (1 paper, 2020). "Taken together, these results showed that the expression of LUZP2 decreased significantly with the increase of tumor malignancy." (PMID 32695826, 2020). "However, the expression of the LUZP2 mRNA level decreased gradually with the increase of tumor grade." (PMID 32695826, 2020). "LUZP2 expression was downregulated with the increase of tumor grade (p < 0.05)." (PMID 32695826, 2020). "Therefore, we have reason to believe that LUZP2 is a good indicator of tumor malignancy." (PMID 32695826, 2020). "When the tumor grade has not increased, LUZP2 has begun to decline and the prognosis has begun to deteriorate." (PMID 32695826, 2020). "The expression of LUZP2 in the nervous system-specific table was disordered, the neuroendocrine function decreased, and the tumor cells were not like nerve cells but closer to stem cells." (PMID 32695826, 2020). "When the tumor level has not increased, LUZP2 has begun to decline and the prognosis has begun to deteriorate." (PMID 32695826, 2020).
LUZP2 also shares sentences with these, for which no sentence is quoted: aniridia (3 papers); mental Retardation (2); WAGR syndrome (2); adenocarcinoma of the lung (1); adrenocortical carcinoma (1); Angelman syndrome (1); astrocytoma of the brain (1); depression (1); hypereosinophilic syndrome (1); lung squamous cell carcinoma (1); peripheral neuropathy (1); prostate adenocarcinoma (1).